NUCB2 (nucleobindin 2)
Diseases named in the same sentence as NUCB2 in open-access papers (continued):
Sharing a sentence is not in itself a finding about the gene and the disease.
colon cancer (continued). "It indicates the NUCB-2/AMPK/TORC1 pathways are upstream pathways of ZEB1 and EMT properties in colon cancer." (PMID 27150059, 2016). "In summary, nesfatin-1/NUCB-2 enhanced migration, invasion and EMT in colon cancer cells through LKB1/AMPK/TORC1/ZEB1 pathways in vitro and in vivo." (PMID 27150059, 2016). "Because high NUCB-2 expression was observed in clinical colon tumor samples and SW620 was a metastatic colon cancer cell line, SW620 was used in this study and two NUCB-2 knockdowned stable clones were established (5524-3 and 5524-4)." (PMID 27150059, 2016). "In addition, they revealed that ZEB-1 had a critical role in NUCB-2- mediated migration, invasion and EMT pathways in colon cancer." (PMID 34361082, 2021). "It suggests that nesfatin-1/NUCB-2 locally but not systematically regulates signaling pathways of colon cancer cells." (PMID 27150059, 2016). "In addition, we demonstrated nesfatin-1/NUCB-2 enhanced migration, invasion and mesenchymal phenotype in colon cancer through LKB1/AMPK/TORC1/ZEB1 pathways." (PMID 27150059, 2016). "Furthermore, studies on colon cancer tissues have demonstrated elevated NUCB2 levels compared to non-tumor tissues." (PMID 40964608, 2025). "Over the last years, NUCB-2 has been discovered related to energy homeostasis, e.g. energy expenditure and glucose homeostasis, and the energy stress might be a key factor in controlling AMPK/TORC1 pathways in NUCB-2 knockdown colon cancer cells." (PMID 37635259, 2023). "Interestingly, the inhibition of NUCB2 with siRNA in colon cancer cells did not affect proliferation." (PMID 36012443, 2022). "Interestingly, no changes were found in the proliferation properties of NUCB2-knockdown colon cancer cells." (PMID 34361082, 2021). "In this study, NUCB-2 level in colon cancer tissue was higher than that in non-tumor tissue." (PMID 27150059, 2016). "Thus, we hypothesized that NUCB-2 enhanced migration, invasion, and EMT pathways in colon cancer." (PMID 27150059, 2016).
bladder cancer (11 papers, 2020 to 2025). "This is consistent with NUCB2 knockdown in bladder carcinoma cells, which inhibits invasion and proliferation." (PMID 38760405, 2024). "Bladder cancer cell lines, transfected with Nucb2-targeted shRNA to knockdown Nucb2 expression, were characterized in order to verify the effects of Nucb2 on cell proliferation and invasion." (PMID 34073612, 2021). "The results of the assays revealed that the knockdown of Nucb2 with special shRNA inhibits invasion and proliferation in bladder cancer cells." (PMID 34073612, 2021). "The study results also demonstrated that NUCB2/NESF-1 shRNA-silenced bladder cancer cell lines had a lower migration and invasion ability than controls." (PMID 34361082, 2021). "According to results obtained from multivariate analysis, it was concluded that NUCB2/NESF-1 was the overall survival (OS) independent prognostic factor of bladder cancer." (PMID 34361082, 2021). "However, recent in vitro studies showed that NUCB2/NESF-1 knockdown with siRNA or shRNA in bladder cancer, glioblastoma, endometrial cancer, and thyroid cancer cell lines resulted in the inhibition of cell proliferation." (PMID 36012443, 2022). "NUCB2/nesfatin-1 has been reported to promote cell proliferation, migration, and invasion in various cancers, including breast, colon, prostate, endometrial, thyroid, and bladder cancers." (PMID 36585713, 2022). "Nucleobindin 2 (NUCB2) codifies for a calcium-binding protein, and its overexpression has been related to tumor growth, cell proliferation, migration and invasion in prostate cancer, bladder cancer and RCC." (PMID 35813211, 2022). "The expression levels of MMP-2 and MMP-9 in bladder cancer cells transfected with Nucb2 shRNA was lowered, indicating that Nucb2 may affect cancer migration and invasion through the MMP-2 and MMP-9 signaling pathways." (PMID 34073612, 2021). "Recently, it has been demonstrated that high expression of NUCB2/NESF-1 is associated with poor outcomes and promotes cell proliferation, migration, and invasion in, e.g., breast, colon, prostate, endometrial, thyroid, bladder cancers, or glioblastoma." (PMID 34361082, 2021). "Moreover, in vivo studies also showed that the knockdown of Nucb2 might decrease tumor growth, at least in the case of thyroid and bladder cancer cells." (PMID 34073612, 2021).
endometrial cancer (11 papers, 2017 to 2025). Primary or metastatic malignant neoplasm involving the endometrium (mucous membrane that lines the endometrial cavity). "While some studies report high NUCB2/nesfatin-1 expression in endometrial cancer, others show low serum nesfatin-1 levels in endometriosis." (PMID 40144052, 2025). "Some studies report high expression of NUCB2/nesfatin-1 in type I and type II endometrial cancer tissue while others report an inverse correlation between nesfatin-1 and endometriosis, as serum nesfatin-1 remains low in patients with endometriosis." (PMID 39455994, 2024). "Generally, a high expression of nucleobindin-2/NESF-1 is associated with poor outcomes in breast, colon, bladder, prostate, gastric, renal, and endometrial cancer." (PMID 36012443, 2022). "In addition to being correlated with reproductive disorders, NUCB2/nesfatin-1 has been noted to be involved in the development of endometriosis, endometrial cancer and ovarian cysts." (PMID 40144052, 2025). "Similarly, nesfatin-1 enhances proliferation and migration in the endometrial carcinoma cell line Ishikawa, while NUCB2 knockdown via siRNA impairs these processes." (PMID 40964608, 2025). "In addition to metabolic diseases, NUCB2/nesfatin-1 has been involved in reproductive disorders such as endometriosis and endometrial cancer." (PMID 39455994, 2024). "Similarly, in endometrial carcinoma cells, Nucb2 and its derivative nesfatin-1 significantly induced cell proliferation and migration." (PMID 34073612, 2021). "The suppression of NUCB2/NESF-1 with siRNA inhibited migration and invasion in the colon, renal, Ishikawa, and Sawano endometrial cancer cells." (PMID 34361082, 2021). "Immunoreactivity of NUCB2/NESF-1 was detected in 22% of endometrial carcinomas and significantly higher than non-neoplastic endometrial glands." (PMID 34361082, 2021). "In addition, a positive correlation was found between the expression of NUCB2/NESF-1 and EMT-related genes such as desmoplakin (DSP), Integrin Subunit Alpha V (ITGAV), metalloproteinase 3 (MMP3), tetraspanin 13 ( TSPAN13), and Cadherin 2 (CDH2) in endometrial cancer cells." (PMID 34361082, 2021). "Similarly, in endometrial carcinomas, the immunoreactivity of NUCB2/nesfatin-1 is significantly higher than that in non-neoplastic endometrial glands." (PMID 40964608, 2025).
osteoarthritis (11 papers, 2013 to 2024). A noninflammatory degenerative joint disease occurring chiefly in older persons, characterized by degeneration of the articular cartilage, hypertrophy of bone at the margins and changes in the synovial membrane. "Third, the effect of NUCB2 on SFs should be explored in other control cells (osteoarthritis-SFs) to clarify the specificity of the effect of NUCB2 in RASFs." (PMID 36585713, 2022).
prostate carcinoma (11 papers, 2013 to 2023). A carcinoma that arises from epithelial cells of the prostate gland. "High levels of NUCB-2 mRNA and protein is associated with shorter biochemical recurrence-free survival time in prostate cancer." (PMID 27150059, 2016). "Currently, it is known that NUCB2 positively correlates with the Gleason grade in prostate cancer and the Fuhrman grade in renal cancer." (PMID 36012443, 2022). "Immunohistochemistry evaluation revealed that NUCB2/NESF-1 expression was significantly higher in prostate cancer compared to benign prostatic hyperplasia (p < 0000.1)." (PMID 34361082, 2021). "In other studies, the same research team showed that high NUCB2/NESF-1 mRNA expression was related to the poor overall survival of patients with prostate cancer." (PMID 34361082, 2021). "The upregulation of NUCB2/NESF-1 mRNA in prostate cancer was correlated with higher Gleason scores (p < 0000.1), higher levels of preoperative prostate-specific antigen (PSA) (p = 0.0004), positive lymph node metastasis (p = 0.022) and positive angiolymphatic invasion (p = 0.0004)." (PMID 34361082, 2021). "In addition, multivariate Cox analysis indicated that NUCB2/NESF-1 mRNA was an independent prognostic factor for the overall survival of prostate cancer patients." (PMID 34361082, 2021). "Additionally, NUCB2 was up-regulated in prostate cancer and served as a prognostic biomarker." (PMID 32226311, 2020). "Multivariate Cox regression analysis revealed that a high NUCB2/NESF-1 protein expression level was an independent prognostic factor for overall survival and BCR-free survival of patients with prostate cancer." (PMID 34361082, 2021). "However, the role of NUCB2 in prostate cancer (PCa) remains unclear." (PMID 23958433, 2013). "The NUCB2/NESF-1 mRNA level was analyzed in 180 pairs of prostate cancer tissues and the corresponding noncancerous tissue." (PMID 34361082, 2021). "To date, there have been no published data regarding the role of NUCB2 protein expression in prostate cancer (PCa)." (PMID 24422979, 2013).
gastric cancer (10 papers, 2013 to 2025). A primary or metastatic malignant neoplasm involving the stomach. "For instance, NUCB2/nesfatin-1 enhances the cell proliferation, migration, invasion and epithelial–mesenchymal transition in gastric carcinoma." (PMID 40964608, 2025). "The NUCB2 protein was found in the nuclei and the cytoplasm in thyroid and gastric cancer, while NUCB2 expression in BC was limited to the cytoplasm." (PMID 36012443, 2022). "This study aimed to explore the functional role of NUCB2/nesfatin‐1 in the cell proliferation, migration and invasion in gastric carcinoma (GC)." (PMID 36065769, 2022). "The immunohistochemistry analysis revealed that NUCB2/NESF-1 in gastric cancer cells was predominantly localized in the nuclei and its expression was higher in tumor tissues than in the adjacent normal tissues." (PMID 34361082, 2021). "In this study, we used iTRAQ and PRM-based quantitative proteomics to detect four saliva protein biomarkers of gastric cancer, including S100A8, S100A9, NUCB2, and CST4, which make them potential novel biomarkers for the noninvasive diagnosis of GC." (PMID 41164825, 2025). "Here, we focused on the role of Nucleobindin 2 (NUCB2), a multifunctional protein, in gastric carcinoma (GC) progression." (PMID 38760405, 2024). "To conclude, NUCB2/NESF-1 might be used as a new biomarker and a potential therapeutic target for gastric cancer." (PMID 34361082, 2021).
melanoma (8 papers, 2018 to 2024). A malignant, usually aggressive tumor composed of atypical, neoplastic melanocytes. "Upregulation of NUCB2 was associated with the inhibition of apoptosis and promotion of cell metastasis in melanoma cells." (PMID 36874361, 2023). "Although an elevated level of Nucb2 was shown to be linked to the inhibition of ERm-stress-induced apoptosis and the promotion of cell metastasis in melanoma, the detailed regulations governing the downstream pathway of Nucb2 still need to be investigated." (PMID 34073612, 2021). "The deficiency of KLF4 decreased lung metastatic abilities of melanoma cells, which was reversed by NUCB2 overexpression." (PMID 30055641, 2018). "Inhibition of miR-610 attenuated LINC00511 deficiency-induced decrease of NUCB2 in melanoma cells." (PMID 36874361, 2023). "Elevated KLF4 was found in human melanoma tissues, which was associated with NUCB2 expression." (PMID 30055641, 2018). "Elevated KLF4 was found in human melanoma tissues, which was associated with NUCB2 upregulation." (PMID 30055641, 2018). "However, whether over-expression of NUCB2 could reverse the suppressive effect of LINC00511 deficiency on melanoma progression should be investigated in further research." (PMID 36874361, 2023). "Loss of LINC00511 inhibited proliferation, metastasis, and epithelial–mesenchymal transition of melanoma through the increase of miR-610 and the decrease of NUCB2." (PMID 36874361, 2023). "Silence of LINC00511 reduced expression of NUCB2 in melanoma cells, and inhibition of miR-610 attenuated LINC00511 deficiency-induced decrease of NUCB2." (PMID 36874361, 2023). "In conclusion, silence of LINC00511 reduced cell proliferation and metastasis of melanoma through down-regulation of miR-610-mediated NUCB2." (PMID 36874361, 2023). "Recently, Nucb2 was also reported to involve metastasis in the melanoma cells by adapting to endoplasmic reticulum (ERm) stress." (PMID 34073612, 2021). "Our previous study showed that KLF4 promoted melanoma cell metastasis by transcriptionally regulating NUCB2 expression." (PMID 33935281, 2021). "Whereafter, we overexpressed NUCB2 into KLF4 KO Mel-RM cells and found that the effects of KLF4 depletion on melanoma adaptation to ER stress and metastasis were reversed by NUCB2 overexpression." (PMID 30055641, 2018). "In our study, we uncovered the oncogene role of NUCB2 in melanoma and found that NUCB2 was induced by ER stress for the first time." (PMID 30055641, 2018). "Compared with the control cells, deficiency in NUCB2 promoted ER stress-induced apoptosis and decreased cell migration, which was consistent with the role of KLF4 in melanoma cells." (PMID 30055641, 2018). "Taken together, these data indicate that the effects of KLF4 on melanoma adaptation to ER stress and metastasis were dependent on NUCB2." (PMID 30055641, 2018). "Although the role of NUCB2 was indicated in our study, the downstream pathway of NUCB2 in melanoma will be explored in the future." (PMID 30055641, 2018). "In melanoma, NUCB2 overexpression suppressed ER stress-induced cell death." (PMID 39309426, 2024). "Reportedly, NUCB2 plays an important role in adaptation to ER stress in melanoma cells." (PMID 33939297, 2021). "In addition, our data demonstrated that ITIH5 was a bona fide interacting protein of KLF4 that suppressed the transcriptional activity of KLF4 and downregulated its target gene NUCB2, leading to the suppression of melanoma." (PMID 33935281, 2021). "The findings presented above indicate that Nucb2 might be involved in melanoma cell metastasis through ERm stress induction." (PMID 34073612, 2021). "Moreover, IHC studies revealed that the expression of NUCB2 was positively correlated with KLF4 in melanoma tissues." (PMID 34361082, 2021). "Interestingly, KLF4 was shown to regulate transcription of NUCB2 by binding to its promoter which induced melanoma ER stress resistance, tumor growth, and cell metastasis in vitro and in vivo." (PMID 34068679, 2021).
melanoma (continued). "We found that KLF4 induced by ER stress could directly bind to the promoter of NUCB2 and promote NUCB2 expression, leading to the increase in melanoma ER stress resistance and cell metastasis." (PMID 30055641, 2018). "Therefore, LINC00511/miR-610/NUCB2 was a potential target of melanoma." (PMID 36874361, 2023). "Therefore, LINC00511 might contribute to melanoma progression through upregulation of miR-610-mediated NUCB2." (PMID 36874361, 2023). "Moreover, a higher level of KLF4 correlates with elevated NUCB2 in human melanoma tissues, suggesting that NUCB2 may be important in the regulation of melanoma metastasis under ER stress." (PMID 34068679, 2021). "Furthermore, our data also showed that elevated NUCB2 plays an important role in inhibiting ER stress-induced apoptosis and promoting cell metastasis in melanoma, and the expression level of NUCB2 was increased in melanoma tissues." (PMID 30055641, 2018). "Based on this, we assessed the effect of ITIH5 on the expression of NUCB2, a known target gene of KLF4, in melanoma cells." (PMID 33935281, 2021). "We found that the relative expression levels of KLF4 and NUCB2 were significantly increased in melanoma tissues, and the protein level of KLF4 was positively correlated with NUCB2 in melanoma tissues." (PMID 30055641, 2018).
glioblastoma (6 papers, 2021 to 2025). The most malignant astrocytic tumor (WHO grade IV). "Collectively, these longitudinal data corroborate the EdU assay results and underscore the pivotal role of NUCB2 in maintaining the enhanced proliferative capacity characteristic of glioblastoma cells." (PMID 40913484, 2025). "NUCB2 has been reported to promote the proliferation and invasion of glioblastoma cells in vitro and enhance tumor growth and metastasis in vivo." (PMID 40964608, 2025). "Our extensive analysis of the spatial molecular heterogeneity of glioblastoma identifies NUCB2 as a critical regulator situated at the intersection of tumour cell proliferation and immune evasion." (PMID 40913484, 2025). "Future studies focusing on the effects of NUCB2 overexpression on in vivo tumor growth would provide valuable insights into its role in glioblastoma progression." (PMID 37830634, 2023). "On the contrary, it has been revealed that NUCB2/nesfatin‐1 was predominantly expressed in the nucleus of glioblastoma cells." (PMID 36065769, 2022). "Lower invasion and migration properties were found in NUCB2/NESF-1-knockdown glioblastoma cells." (PMID 34361082, 2021). "The IHC staining showed that NUCB2/NESF-1 was predominantly expressed in the nucleus and was highly overexpressed in glioblastoma compared to the adjacent tissue." (PMID 34361082, 2021). "Since then, there have been single reports on NUCB2/NESF-1 in the most common human cancers, i.e., breast, colon, gastric, bladder, ovarian, endometrial, prostate, papillary thyroid cancers, renal cell carcinoma, and glioblastoma." (PMID 34361082, 2021).
Hypertension (6 papers, 2020 to 2025). The presence of chronic increased pressure in the systemic arterial system. "Based on the single-tissue eQTL in GTEx, the NUCB2 rs757081 and AGT rs699 decreases their gene expression levels in several tissues and both SNPs have been associated with hypertension in the GWAS catalogue." (PMID 32171244, 2020). "The expression of NUCB2 mRNA was shown to be increased in the media of the aorta of hypertensive rats, so it may have a role in development of hypertension." (PMID 31339256, 2020). "In individuals diagnosed with essential hypertension, it has been observed that circulating levels of NUCB2/Nesfatin-1 are higher compared to normotensive individuals." (PMID 39335642, 2024).
ovarian carcinoma (6 papers, 2021 to 2025). A malignant neoplasm originating from the surface ovarian epithelium. "We found that the expression of BANF1, CDK2AP2, DDT, LRIG1, MRPL4, and S100A13 was upregulated in ovarian cancer samples, and the expression of EPS8, NUCB2, PAF1, PMP22, RABGAP1L, and USO1 was upregulated in normal samples." (PMID 41000388, 2025).